TNF (tumor necrosis factor)
Diseases named in the same sentence as TNF in open-access papers (continued):
Sharing a sentence is not in itself a finding about the gene and the disease.
breast carcinoma (continued). "TNF-α may serve as a potential therapeutic target in breast cancers susceptible to TNF-α stimulation." (PMID 27042827, 2016). "Interestingly, breast cancer treatment with chemotherapeutic agents has been found to increase CAEC-derived production of tumor necrosis factor (TNF)-alpha, causing an increase in production of CXCL1/2 via nuclear factor (NF)-kappaB by the cancer cells." (PMID 27515302, 2016). "Several studies have shown a close link between TNFα -308G > A polymorphism and breast cancer risk." (PMID 26112140, 2015). "We genotyped 100 premenopausal Eastern European (Lithuanian) patients with stage I-II breast cancer, ≤50 years old at the time of diagnosis, for interleukin 10 -592A > C, −819C > T and -1082A > G and tumor necrosis factor α -308G > A single nucleotide polymorphisms in the gene promoter region." (PMID 26112140, 2015). "This study analyzes single nucleotide polymorphisms in interleukin 10 and tumor necrosis factor α genes and their contribution to breast cancer phenotype, lymph node status and survival in a group of young Lithuanian women with early-stage breast cancer patients." (PMID 26112140, 2015). "To investigate whether the TIMP3 deficient mammary tumor phenotype involves TNF we undertook a genetic approach." (PMID 25807548, 2015). "NFKB1, NFKBIA, IL-8, IL-10, and TNF polymorphisms could serve as useful predictive biomarkers for breast cancer risk among women in East China." (PMID 25559835, 2014). "The strongest synergistic association on breast cancer ER status was found between 25OHD and TNFα." (PMID 24473087, 2014). "However, in breast cancer, TNF-α resistance was also associated with SLUG[GenBank:GJ062364] upregulation." (PMID 23339680, 2013). "Moreover, one of the well-established dose-limiting toxicities associated with docetaxel chemotherapy in breast cancer patients is fatigue, and high TNF levels have been shown to correlate with fatigue onset in cancer patients." (PMID 22225778, 2012). "The exact role of TNF genetic variation on mammographic density is thus unclear, however, if inflammation is an important aspect of breast cancer development, then it seems reasonable that TNF variants may play a role." (PMID 23095343, 2012). "Likewise, tumor stromal TNF-α has been shown to be associated with highly invasive breast carcinoma." (PMID 22529912, 2012). "In the present study, we show that the CD44 variant isoform 4 (CD44v4) is a major metastatic breast cancer cell glycoprotein decorated with sLex moieties and serves as an E-selectin ligand in facilitating tumor cell migration across TNF-α pre-activated HUVEC monolayers." (PMID 18350162, 2008). "Furthermore, TAMs activate the NF-κB/STAT3/ERK signaling pathway in tumor cells by secreting pro-inflammatory cytokines such as TNF-α and IL-6, which are responsible for the phosphorylation and activation of ERα, causing endocrine therapy resistance of breast cancer." (PMID 37900137, 2023). "TNF-induced nuclear localization of the gene glioma-associated oncogene homologue-1 (Gli1) and genetic expressions into mRNA and protein that inhibited TNF-induced migration and invasion in human breast cancer cells have been studied extensively using DAI to control Hh-signaling." (PMID 36838751, 2023). "Whereas TNFα and IL-1β are minimally expressed in normal breast tissues, their expression levels in breast cancer patients are relatively high, and are increased as disease progresses, and studies in breast cancer animal models provided evidence to their causative roles in promoting disease course." (PMID 35884574, 2022).
breast carcinoma (continued). "However, one case-control study nested within the Malmö Diet and Cancer Cohort found an inverse association between high levels of TNF-α and breast cancer risk [ORT3 vs T1=0.65 (0.43–0.99)] while the CLUEII study noted a positive association between TNF-α and breast cancer risk." (PMID 35430795, 2022). "Thus, to estimate whether HDACs are also associated with apoptosis after TNF-α treatment in breast cancer cells, their expression levels and activities were assessed." (PMID 32455774, 2020). "On the basis of these facts, the downregulation of ERα expression by TNF-α treatment may contribute to overcoming the resistance to chemotherapy in patients with ERα-positive breast cancer; however, the molecular mechanism underlying this phenomenon remains unclear." (PMID 32455774, 2020). "The ER-positive MCF-7 cells belongs to luminal breast cancer subtype with an epithelial phenotype and the changes in the expression of GT genes that we observe in this study could be therefore associated with TNF-induced EMT of MCF-7 cells." (PMID 29698439, 2018). "Interestingly, a factor that contributes significantly to breast cancer susceptibility is the presence of a polymorphism of TNF-α (TNF-α-308) located in the promoter region of the gene, that involves the substitution of a guanine by an adenine, as reported in caucasian and mexican women." (PMID 29202842, 2017). "On the contrary, the TNFα -308 polymorphism might modulate the risk and contribute to the identification of patients at a higher risk of breast cancer recurrence, metastasis and worse overall survival among young Lithuanian early-stage breast cancer patients." (PMID 26112140, 2015). "Contrary, the TNFα -308 polymorphism might modulate the risk and could contribute to the identification of patients at a higher risk of BC recurrence, metastasis and overall survival in Lithuanian early-stage breast cancer patients." (PMID 26112140, 2015). "Thus, these two steroid receptors may be involved in the carcinogenesis of breast cancer, and their roles in invasion and metastasis of breast cancer are probably associated with the expression of NF-κB and TNF-α." (PMID 24864130, 2014). "In light of such mechanisms, we may need to consider the use of inhibitors of mutated (i.e., hyper-activated) Ras in patients who do not have any apparent constitutive activation of the oncogene due to its mutation and also express high levels of TNFα, as is the case for many breast cancer patients." (PMID 24598028, 2014). "MCs are derived from common progenitor cells and are activated in breast cancer angiogenesis, where they generate TNF, proteases, IL-1, and IL-6, which induce inflammation." (PMID 41596472, 2026). "In breast cancer, high circulating TNF-α has likewise been identified as an independent predictor of poorer survival." (PMID 40299527, 2025). "The study examined the regulation of PD-1, PD-L1, MMP-9, AGEs, AOPPs, IL-6, 8-OHdG and TNF-α expression in a rat model of breast cancer induced by DMBA." (PMID 40008130, 2025). "Multicenter RCTs should also explore the impact of exercise interventions on biomarkers like CRP, IL-6, and TNF-α for breast cancer patients to validate broader applicability of results." (PMID 41280723, 2025). "Roubert et al177 demonstrated a positive correlation between BMI and the secretion of IL-1, IL-6, and TNF-α, which promote breast cancer by stimulating wingless/integrated (Wnt) signaling in mammary tissue." (PMID 40584290, 2025). "In breast cancer, TNF-α induces Gli1 nuclear translocation, elevates MMP-9 expression, and drives cell invasion to confer resistance." (PMID 41450917, 2025). "CMTM1-v17 prevents TNF-α-induced apoptosis by activating the NF-kB pathway and promoting cellular proliferation in breast cancer." (PMID 40179060, 2025). "In this study, treatment of MCF‐7 breast cancer cells with SL extract led to a significant, dose‐dependent increase in several key cytokines, including TNF‐α, TGF‐β, IL‐1β, DEF‐β, and IFN‐γ." (PMID 40685820, 2025).
breast carcinoma (continued). "In the adipose tissue of postmenopausal women with breast cancer, TNF-α increased the expression of aromatase, which in turn boosted estrogen." (PMID 40584290, 2025). "Specifically, we investigated the effects of TNF EVs on breast cancer cells’ proliferation, migration, and therapy resistance." (PMID 40567500, 2025). "Silibinin also regulates cytokine secretion, increasing IL-12 and IFN-γ levels while reducing TGF-β, SDF-1, IL-6, and TNF-α, all of which play crucial roles in immune regulation and anti-cancer immunity in 4T1 breast cancer bearing mice." (PMID 40490812, 2025). "An article reported that the levels of IL-6 and TNF-α in the serum of breast cancer patients lowered vitally after AE, determining that AE can positively modulate the levels of these pro-inflammatory factors." (PMID 41480347, 2025). "In summary, our study emphasizes the vital role of EVs derived from TNF-α conditioned macrophages in advancing breast cancer progression, metastasis, and endocrine resistance." (PMID 40567500, 2025). "In summary, TNF-α clearly plays a role in the biology of breast cancer, but more research is needed to validate it as an independent prognostic biomarker and as a safe therapeutic target in this setting." (PMID 41007766, 2025). "This is a new and comprehensive study for the effects of TNF-α on VGCC of MCF-7 breast cancer cells." (PMID 41415204, 2025). "While the control group generally exhibited low baseline levels of circulating cytokines, breast cancer patients demonstrated significantly elevated concentrations of multiple cytokines, including IL-1β, IL-6, IL-8, IL-12 (p40), IL-13, G-CSF, TNF-α, and MCP-1." (PMID 40612845, 2025). "Tob knockdown in human breast cancer cells promoted overactivation of NF-κB upon TNF-α treatment, whereas overexpression of Tob inhibited TNF-α stimulation-dependent NF-κB activation." (PMID 40169858, 2025). "In breast cancer, TNF-α is believed to have a context-dependent role, exerting both tumor-promoting and tumor-suppressing effects." (PMID 41325308, 2025). "Our findings demonstrate a significant upregulation of key pro-inflammatory cytokines such as IL-6, IL-1β, TNF-α, and IL-12 (p40) in the plasma of breast cancer patients, with expression correlating positively with tumor stage and grade." (PMID 40612845, 2025). "In this study, the objective was to evaluate the prognostic relevance of serum levels of IL-6 and TNF-alpha in survival and treatment response in women with breast cancer." (PMID 40558287, 2025). "The aim of this study was to evaluate the prognostic relevance of serum IL-6 and TNF-alpha levels on survival and treatment response in women with breast cancer." (PMID 40558287, 2025). "In breast cancer, tumor-derived factors such as tumor necrosis factor-α (TNF-α) reprogram pDCs leading to impaired interferon (IFN)-α production." (PMID 40165290, 2025). "Clinical investigations and in vitro and in vivo animal studies have shown that TNF-α drives breast cancer by inducing the upregulation of oncogenes." (PMID 40430573, 2025). "In breast cancer, the TME is inhibited by increased levels of cytokines, including TNF-α and IL-6, which are associated with both immunosuppression and tumorigenesis." (PMID 40008130, 2025). "We compared how Donor 216T and 192D CD8+ T cells transduced with the MC.7.G5 TCR ± TCR replacement and the MC.7.G5 T cell clone recognized the MR1*01/*02 breast cancer cell line MCF-7 using TNF as a readout." (PMID 39744940, 2025). "Similar to our findings, dysregulated plasma levels of IL-6, IL-8 and TNF-α have also been observed in patients with CRCI in breast cancer and hematological malignancies." (PMID 40597835, 2025).
breast carcinoma (continued). "TNF-α and NFkB signaling pathway activities were elevated in malignant cells of primary breast cancer samples compared to those of metastatic samples." (PMID 40858590, 2025). "For example, in breast cancer models, treatment with chemotherapy was found to induce TNF-α activation of NF-κB to increase CXCR1/2 expression, to reduce sensitivity to therapy." (PMID 40299479, 2025). "We focused on IL-2, IL-6, IL-10, and TNF-α due to their well-documented relevance in breast cancer immunobiology, as reported in previous studies." (PMID 40869161, 2025). "Blocking TNF-α signaling, decreased breast cancer metastasis to lungs in mice by ~ 60%, and decreasing TNF-α signaling, decreased NF-κB activation and the expression of inflammation-related genes that regulate metastasis." (PMID 40343927, 2025). "Unlike IL-6 or IL-1, there have been few, if any, clinical trials specifically testing anti-TNF agents (such as infliximab or etanercept) in breast cancer patients." (PMID 41007766, 2025). "Considering the comprehensive effects of PCNA and TNF-α described throughout this study as primary targets of skimmianine, their suppression underscores their relevance as actionable therapeutic nodes in breast cancer." (PMID 40430573, 2025). "This study provides initial evidence supporting the potential of skimmianine to modulate tumor proliferation and immune dynamics in breast cancer through PCNA- and TNF-α-associated mechanisms." (PMID 40430573, 2025). "The findings provide credence to the possibility that the TNF-α-308G > A (rs1800629) SNP contributes to the development of breast cancer in the Egyptian population under investigation." (PMID 39570546, 2025). "TNF-α initiates a pro-tumor program in breast cancer cells, increasing proliferation and IL-6/IL-8 and VEGF production in these cells." (PMID 41584509, 2025). "Critically, BPA-exposed adipocytes show increased expression of inflammatory cytokines, IL-6, IL-1β, and TNFα, which are known to activate key oncogenic pathways in breast cancer cells, such as STAT3 and NF-κB." (PMID 40034592, 2025). "Yenidogan et al207 conducted a randomized trial and found that elderly breast cancer patients who received β-glucan treatment had significantly lower levels of TNF-α and IL-6." (PMID 40584290, 2025). "Another EMT-inducing factor, tumor necrosis factor-α (TNF-α), is an important proinflammatory cytokine that is highly upregulated in breast cancer cells and secreted by stromal cells." (PMID 40833805, 2025). "When 164 breast cancer patient samples were tested when they were menopausal, researchers discovered a favorable link between the expression of TNF-α and IL-6 and breast cancer cells." (PMID 40584290, 2025). "Elevated NDUFB1 expression correlated with improved relapse-free survival in breast cancer, while its regulation by TNF-α differed between ER-positive and triple-negative cell lines." (PMID 41157129, 2025). "Following our observations that TNF EVs enhance the proliferation of MCF-7 ER+ breast cancer cells, we next assessed their impact on cell migration." (PMID 40567500, 2025). "In contrast, primary breast cancer samples displayed increased activation of the TNF-α signaling pathway via NF-kB, indicating a potential therapeutic target." (PMID 40858590, 2025). "A recent study found that serum levels of cytokines, such as TNF-α, IL-6, IL-8, and IL-10, differ significantly between patients with breast cancer menopause and controls." (PMID 40584290, 2025). "Chronic inflammation, driven by higher levels of inflammatory cytokines such as TNF-α and IL-6 as well as telomere shortening, significantly contributes to the aging characteristics of breast cancer survivors." (PMID 40075712, 2025). "They discovered a strong correlation between ox-LDL, IL-1β, and TNF-α and post-menopausal breast cancer." (PMID 40584290, 2025).
breast carcinoma (continued). "Two of these genes (RIPK1 and TNF) were recently reported as part of a three-gene signature that identifies breast cancer patients that benefit from the IAP inhibitor LCL161, administered in combination with paclitaxel." (PMID 40694850, 2025). "This study focused on the impact of EVs secreted by TNF-α conditioned macrophages (TNF EVs) on ER+ breast cancer cells, specifically the MCF-7 cell line." (PMID 40567500, 2025). "Our earlier research showed that TNF-α conditioned macrophages and their secreted factors boost the proliferation, migration, invasion and endocrine resistance of ER+ breast cancer cells." (PMID 40567500, 2025). "The clinical trial also identified a significant reduction in serum TNF-α levels in breast cancer patients (pre-PBMT = 82.13 ± 14.54 pg/mL; post-PBMT = 17.05 ± 2.267 pg/mL; p = 0.0045)." (PMID 40172371, 2025). "First, a correlation has been found between TNF-α levels at the tumor site or in the plasma/serum of breast cancer patients, their clinical status, and outcomes." (PMID 40558287, 2025). "Third, TNF-α is involved in epithelial–mesenchymal transition and breast cancer cell metastasis, contributing to the development of drug resistance." (PMID 40558287, 2025). "In breast cancer, it decreases tumor necrosis factor-α (TNF-α), interleukin-6 (IL-6), and CRP while enhancing metabolism and immunity." (PMID 41280723, 2025). "Our study also sheds light on the role of TNF EVs in expanding the population of tumor stem cells within the breast cancer cell line MCF-7." (PMID 40567500, 2025). "One of the key findings of our study is the ability of TNF EVs to enhance the proliferative and migratory capacities of ER+ breast cancer cells." (PMID 40567500, 2025). "No preclinical or clinical evidence was found regarding the efficacy of TNF-alpha antibodies in breast cancer patients." (PMID 40558287, 2025). "This strongly suggested that increases in TNF‐α in the prefrontal cortex were a consequence of active breast cancer and sustained tumour growth." (PMID 40172096, 2025). "A large case–control study in France found that breast cancer patients had significantly higher serum TNF-α levels than healthy controls, and TNF-α levels were positively associated with cancer risk, with an OR of ~2.0 for the highest vs. the lowest quartile." (PMID 41007766, 2025). "Regarding its mechanism, several studies have suggested that increased expression of A20 in breast cancer suppresses TNFα-induced apoptosis, thereby promoting tumor growth and metastasis." (PMID 40214497, 2025). "The immune regulatory roles of PCNA and TNF-α in breast cancer were further examined through immune correlation analyses of their skimmianine-associated hub proteins." (PMID 40430573, 2025). "Increased concentrations of inflammatory cytokines such as interleukin-6 (IL-6) and tumor necrosis factor-α (TNF-α) in breast cancer patients promote tumor progression, angiogenesis, and invasion." (PMID 40720508, 2025). "Secreted mainly by TAMs and tumor cells, TNF-α plays a significant role in breast cancer progression by facilitating epithelial-to-mesenchymal transition (EMT), metastasis, and endocrine resistance." (PMID 40567500, 2025). "Here, we investigated the roles of TGF-β1 and TNF-α in the recruitment of neutrophils by breast cancer cells." (PMID 40833805, 2025). "In contrast, efforts to therapeutically inhibit TNF-α in breast cancer have yielded limited success." (PMID 41007766, 2025). "TNF-α, a pro-inflammatory cytokine, is highly expressed in breast carcinomas, where its chronic expression fosters carcinogenesis and tumor growth." (PMID 41153842, 2025). "The wound healing assay demonstrated that TNF EVs significantly promote the migration of breast cancer MCF-7 cells." (PMID 40567500, 2025).